BAD (BCL2 associated agonist of cell death)
Diseases named in the same sentence as BAD in open-access papers (continued):
Sharing a sentence is not in itself a finding about the gene and the disease.
cancer (continued). "These are in accordance with the studies by Cheng and Wei that BH3 domain-only molecules, including BAD, were required for the disruption of mitochondrial and intrinsic death of cancer cells." (PMID 23725574, 2013). "Altered Akt/BAD signaling contributes to mitochondrial dysfunction and logically points towards the possible involvement of Akt-associated pathways in GTP-induced cancer cell apoptosis via mitochondrial death cascade." (PMID 23285096, 2012). "The apoptosis was facilitated by the dephosphorylation and activation of proapoptotic BAD protein, likely triggered by the inhibition of several cancer survival pathways, including RAS/MAPK, ERK1/2, and PI3K/AKT, through cannabinoid 1 (CB1) receptor activation." (PMID 38674023, 2024). "Given that BAD is a vital downstream mediator of RAS effector pathways mediating cancer cell survival and apoptosis, targeting its phosphorylation may be and is demonstrated herein, to be advantageous for the treatment of KRAS-mutant PDAC." (PMID 38409090, 2024). "Consequently, aberrant activation of p44/42 MAPK and PI3K/AKT pathways drives site-specific phosphorylation of BAD, promoting the survival of cancer cells." (PMID 38409090, 2024). "Our findings showed that BHE and betanin can stimulate the intrinsic and extrinsic apoptosis pathways in HT-29 and Caco-2 cancer cell lines via downregulation of Bcl-2 and upregulation of BAD and Caspase-9 genes and also upregulation of Fas-R, Caspase-3, and Caspase-8, respectively." (PMID 37464362, 2023). "Interestingly, the expression level of proapoptotic gene BAD, in the HT-29 and Caco-2 cancer cells after treatment with BHE and betanin was even higher than 5-FU as a positive control group." (PMID 37464362, 2023). "The inhibition of glycolysis seriously depletes ATP of cancer cells and leads to the rapid dephosphorylation of glycolysis-apoptosis integrator BAD in Ser112 and the relocalization of BAX to mitochondria, which can effectively induce apoptosis in multidrug resistant cells." (PMID 35408903, 2022). "After 6 h, the total protein was extracted for phosphorylation protein microarray analysis, which found that AKT and GSK3β protein phosphorylation ratios in the sh-cancer-IgG group were reduced and that Bcl-2, BAD, caspase 3, caspase 9, and BAX apoptosis-related proteins increased." (PMID 34150640, 2021). "Hence, as a common downstream cell survival mediator of both the RAS/RAF/MAPK and PI3K/AKT/mTPR pathways, phosphorylated BAD has been demonstrated to be critically involved in cancer development, progression, and therapeutic resistance." (PMID 34681659, 2021). "The design and development of a small molecule named NPB [3-{(4(2,3-dichlorophenyl)piperazin-1-yl}{2-hydroxyphenyl)methyl}-N-cyclopentylbenzamide], which specifically inhibited the phosphorylation of BAD at Ser99 in human carcinoma cells has been previously reported." (PMID 34681659, 2021). "By instead promoting oxidative metabolism, BAD may skew tumor characteristics toward less aggressive cancers, as we identified BAD expression reduced the size of mammospheres, a marker for the stem cell population." (PMID 30635657, 2019). "The dysregulated expressions and phosphorylation of BAD might lead to imbalance of programmed cell death and immortalized cancer cells." (PMID 31920959, 2019). "This understanding of BAD-mediated metabolic effects may yield new insights into cancer therapeutics." (PMID 30635657, 2019). "Interestingly, high-grade tumours exhibit higher BAD protein levels than those with low-grade cancer, suggesting a role in tumour progression." (PMID 29385093, 2018).
cancer (continued). "Therefore, the suppression of BAD phosphorylation by A2M* seems to be a promising target to induce apoptosis in cancer cells." (PMID 29281661, 2017). "Other pro-apoptic proteins belonging to BCL-2 family such a BAX, BAK, PUMA and BAD might also play an important role in the response in oncogene-addicted cancer and activation of apoptosis in NSCLC." (PMID 27926478, 2016). "Our findings suggest that the BAD-mediated apoptotic pathway influences the development of human cancer and that the expression of PP2C may be an important mediator of oncogenic potential." (PMID 25653146, 2015). "The phosphorylation of BAD at Ser-155 is known to contribute to cancer cell survival in vitro." (PMID 25653146, 2015). "Thus, we suggested that BAD overexpression in NSCLC led cancer cells to undergo apoptosis through a mitochondrial pathway." (PMID 23725574, 2013). "One possible explanation could be that AF1q might differently affect BAD expression in different cancer cell types and/or in response only to specific stimuli." (PMID 22761939, 2012). "PI3K activity supports EGF/serum induced survival of cancer cells, through phosphorylation-mediated inactivation of BAD although other kinases could also control Ser75 phosphorylation." (PMID 21880146, 2011). "The balance between BCL-2 and BAD can effect the apoptosis of cancer cell." (PMID 20691103, 2010). "Overexpression of 14-3-3η has been observed in cancers such as breast, lung, liver, and prostate cancer, where it contributes to oncogenic signaling by stabilizing and activating key cancer-related proteins like AKT, RAF, and BAD." (PMID 39407697, 2024). "Collectively, the results herein provide a mechanism-based preclinical and translational rationale, and support a distinct therapeutic opportunity in targeting BAD-mediated survival; and concurrently inhibiting pBADS99 and MEK in KRAS-mutant cancers." (PMID 38409090, 2024). "A latest study found that mitochondrial HK2 prevents mitochondrial translocation of BAD, BAX proteins and activation of caspase-3, thereby alleviating drug-induced pyroptosis of cancer cells." (PMID 38076208, 2023). "With similar fashion in other cancers, HSP (0–100 μM, 24–48 h) triggered apoptosis on human pancreatic cell line through attenuating Bcl-xL but increasing the expression of Bax and BAD and inhibiting cell proliferation via reducing the expression of NF-κβ." (PMID 35128104, 2022). "A broadly observed phenomenon in cancer cells is the constitutive activation of AKT signaling, resulting in BAD phosphorylation, thereby deactivating its pro-apoptotic function (reviewed in reference 48)." (PMID 35577388, 2022). "No significant changes in CASPASE 3/7 activity nor cell viability were observed upon siRNA-mediated depletion of BAD in CAOV2 cells and as previously reported in various carcinoma cells." (PMID 35791346, 2022). "No significant changes in cell viability nor CASPASE 3/7 activity were observed upon siRNA-mediated depletion of BAD in PDO1, as previously reported for various carcinoma cells." (PMID 35791346, 2022). "Hence, SI might have an anti-cancer effect by regulating BAD, caspase-9, Bcl-2, and eNOS." (PMID 34248628, 2021). "BAD Ser-134 was reported to be phosphorylated by RAF, which leads to increased proliferation of cancer cells." (PMID 32612956, 2020). "Particular GFRN members can upregulate anti-apoptotic proteins such as BCL-2, BCL-XL, and MCL-1 and downregulate pro-apoptotic proteins such as BAD, BAX, and BIM, all of which contribute to apoptosis evasion and resistance to cancer treatments in patients." (PMID 28446242, 2017). "In this study, we investigated the influence of the BAD pathway and the expression of PP2C in the development of cancer." (PMID 25653146, 2015).
cancer (continued). "Gos is a natural BH3 mimetics, acting as a small molecule inhibitor for the interaction between anti-apoptotic Bcl-2/Bcl-XL/Mcl-1 and pro-apoptotic BH3-only proteins such as BIM, BID, BAD or BIK, thereby induces apoptosis in cancer cells." (PMID 25231749, 2014). "Although inhibiting 14-3-3ζ triggers apoptosis in cancer cells, there are currently no approved therapeutics that target 14-3-3ζ:BAD interactions." (PMID 41213973, 2025). "In addition to the receptors FGFR1, FGFR4 and ERBB4, the main effector AKT1 and its downstream effectors, MTOR, GSK3B, p21, WEE1, BAD and CREB5, which mediate cancer cell growth and progression, also exhibited marked changes in HPV-ind CCs." (PMID 38253702, 2024). "CBD also led to a significant increase in the expression of pro-apoptotic BAK1, BAX, and BAD in the non-adherent A549 cells, supporting a role for intrinsic mitochondrial apoptosis in cancer stem cells in response to CBD, as reported by others in cancer cells." (PMID 34832951, 2021). "Altogether, this study provides a framework with which to query both normal and neoplastic mammary gland processes and link a non-canonical role of BAD and translation to mammary gland development and cancer pathophysiology." (PMID 34011960, 2021). "Like vincristine, we could detect an increase in priming with BAD, HRK, and MS1 BH3 peptides in CW9019 cells indicating that cancer cells also acquired resistance to doxorubicin treatment through BCL-xL and MCL-1." (PMID 32801295, 2020). "Similarly, the three BAD-SPECIFIC upregulated and the five BAD-SPECIFIC downregulated miRNAs in EXO_BAD were able to modulate 57.5 and 80.3% of the predicted genes included in the “Proteoglycans in cancer” KEGG pathway, respectively." (PMID 33287106, 2020). "In this study, we identify a new lncRNA GOLGA2P10 and reveal that it is induced by ER stress and prevents cancer cells from ER stress-induced apoptosis by upregulating BCL-xL and increasing BAD phosphorylation, indicating GOLGA2P10 as a potential target for cancer therapy." (PMID 32332695, 2020). "The decreased intracellular cAMP would cause inactivation of PKA and its downstream proteins, such as PDE, BAD, HSL, PHK, TH, NAFT, and Filamin, in turn affect the metabolic energy, lipolysis, glycolysis, tyrosine metabolism, and cytoskeletol regulation in cancer cells." (PMID 28117370, 2017). "AKT has been shown to promote cancer cell proliferation and survival by diverse mechanisms including the activation of downstream targets including forkhead transcription factors, GSK3, BAD, Bcl-XL, nuclear factor-kB, and mammalian target of rapamycin (mTOR) kinase." (PMID 24968355, 2014). "14-3-3 proteins are dysregulated in cancers and can act as either tumor suppressors (14-3-3σ) or oncogenes (14-3-3β, ζ, γ, or θ) by binding and sequestering phosphorylated pro-apoptotic proteins such as BAX, BAD, ASK1, Foxo1 or Foxo3a." (PMID 23236401, 2012). "The inhibition rates of EADM and NVB were significantly lower in the BAD negative cancer cells than in the BAD positive cancer cells." (PMID 20691103, 2010). "Depletion of 14-3-3ζ has been found to induce the apoptosis of CRC cells in vitro and in vivo, suggesting that identifying or developing novel inhbitors of 14-3-3ζ that disrupt interactions with BAD may represent a promising approach towards the treatment of CRC and other cancers." (PMID 41213973, 2025).
cancer (continued). "Moreover, vandetanib treatment could decrease the protein expression of MCL‐1 and BCL‐2 and increase the expression of BAD, BAX and BAK in K562 tumor tissues, which was consistent with the regulation of apoptosis‐related proteins in cancer cells in vitro." (PMID 35689424, 2022). "BAD expression did not affect the mammosphere-efficiency but decreased mammosphere area, suggesting that increased tumor volume was not driven by elevated cancer stem cells." (PMID 30635657, 2019). "Thereby, it would not be surprising if cancer cells decrease BAD expression." (PMID 19593445, 2009). "In contrast, loss of proapoptotic effectors, such as the BH3-only proteins BIM, BAD, or NOXA, has no accelerating impact on IR-driven cancer." (PMID 38552015, 2024). "In addition to phosphorylation of BAD at S112 and s136, Mcl1 (or CREB) activated by stress signaling could also inhibit apoptotic, so percent apoptosis in cancer cells was decreased compared to the no-stress condition." (PMID 24339759, 2013).
tumor (117 papers, 2003 to 2026). "Low BAD expression further identified patients at increased risk of recurrence, emphasizing its potential role as a tumor-suppressive marker." (PMID 41514585, 2025). "DSP identified the BCL-2 associated agonist of cell death (BAD) protein as the most significantly upregulated protein in the tumor center." (PMID 39217197, 2024). "293T cells transfected with tumor-associated mutant BAD show decreased apoptosis induction and mutant BAD binds inefficiently to BCL-2 and BCL-XL." (PMID 32335811, 2020). "HRs of 5-year survival curves suggested that TNBC patients were at 2-fold increased risk of death if their tumours expressed increased levels of phospho-BAD-Ser136 or phospho-BAD-Ser155." (PMID 31767884, 2019). "Therefore, the enhanced cellular and tumor growth imparted by BAD-S118D was dependent on S99 phosphorylation and associated with 14-3-3 binding and resistance to apoptosis." (PMID 30635657, 2019). "The inhibition of the pro-apoptotic proteins BAX and BAD by elevated BCL3 expression leads to tumour cell survival and suppressed cytotoxic immune responses." (PMID 40486320, 2025). "An overexpression of NOTCH1 in the tumour microenvironment inactivates Bcl-2-associated X protein (BAX) and Bcl-2-associated Death promoter (BAD) proteins, which help tumour cells survive and prevent immune cells from killing them." (PMID 40672020, 2025). "In tumor-related diseases, STK33 has been shown to suppress mitochondrial apoptosis by inhibiting BAD activity, enhancing tumor cell survival and proliferation." (PMID 40978038, 2025). "As an inhibitor of histone deacetylase 6 (HDAC6), WT161 exerts anti-tumor effects by enhancing the acetylation of histones H3 and H4 on the promoter of the apoptosis-related gene BAD, prompting cell apoptosis and evoking anti-tumor responses." (PMID 38920989, 2024). "The potential targets for Fenticonazole included BAD, which was involved in cell apoptosis, and it was demonstrated that the highest expression levels of BAD were closely correlated with tumor suppression." (PMID 38528462, 2024). "BCL2, a class of anti-apoptotic proteins, modulates apoptosis and promotes survival in tumor cells; While, the pro-apoptotic proteins BAX, and BAD, residing on the mitochondrial membrane is usually downregulated in tumor cells." (PMID 37025487, 2023). "As expected, our gene expression results demonstrated that the triple-drug combination (TME) significantly reduced the levels of BCL2 and enhanced the expression levels of BAX, BAD, caspase-9, 8 and 3 when compared to that of tumor-control group (p < 0.0001)." (PMID 37025487, 2023). "Consistent with the induction of apoptosis, we found a significant decrease in phospho-BAD and Bcl-2 in the tumor tissues of p402 mAb- and p40 mAb-treated PDX mice as compared to those of untreated PDX mice." (PMID 38136341, 2023). "Again, these results were specific, as IgG treatment remained unable to decrease the levels of phospho-BAD and Bcl-2 in the tumor tissues of PDX mice." (PMID 38136341, 2023). "Deficiency of 14-3-3ζ upregulated BAD and BIM and decreased MCL-1 to increase BAX, cleaved caspase 7, and cleaved caspase 3 toward tumor cell anoikis." (PMID 36230714, 2022). "Both gain- and loss-of-function analyses disclosed that GOLGA2P10 increased BCL-xL protein level, promoted BAD phosphorylation, and conferred tumor cells with resistance to ER stress-induced apoptosis." (PMID 32332695, 2020). "The present data validated BAD-dependent tumor growth in a mouse model and demonstrated that this increased tumor growth is sensitive to docetaxel." (PMID 31942016, 2020).